NABP1 (nucleic acid binding protein 1)
Description:
Component of the SOSS complex, a multiprotein complex that functions downstream of the MRN complex to promote DNA repair and G2/M checkpoint. In the SOSS complex, acts as a sensor of single-stranded DNA that binds to single-stranded DNA, in particular to polypyrimidines. The SOSS complex associates with DNA lesions and influences diverse endpoints in the cellular DNA damage response including cell-cycle checkpoint activation, recombinational repair and maintenance of genomic stability. Required for efficient homologous recombination-dependent repair of double-strand breaks (DSBs) and ATM-dependent signaling pathways.
Synonyms: SOSS-B2; hSSB2; OBFC2A; SSB2; FLJ22833; DKFZp667M1322; FLJ13624; MGC111163; NABP1-OT1
Tractability: No criterion of Open Targets' tractability assessment is met for any kind of drug.
Gene: Protein-coding gene on chromosome 2 (191,678,068 to 191,741,097, forward strand). Ensembl gene ENSG00000173559.
Subcellular location: Nucleus
Subcellular location (Human Protein Atlas): Nucleoplasm; Cytosol
Pathways (Reactome):
Gene expression (Transcription): RNA polymerase II transcribes snRNA genes
Gene Ontology:
Molecular function: protein binding; DNA binding; single-stranded DNA binding; RNA binding
Biological process: DNA damage response; DNA repair; double-strand break repair via homologous recombination; mitotic G2/M transition checkpoint; response to ionizing radiation
Cellular component: cytosol; nucleoplasm; nucleus; site of double-strand break; SOSS complex; chromosome, telomeric region
Genetic constraint (gnomAD): Loss-of-function variants: 11 observed, 11.83 expected, observed/expected ratio (o/e) 0.93, 90% interval 0.58 to 1.53. The upper end of that interval is the gene's LOEUF score, 1.53, which puts it in group 6 of 6, group 1 being the genes least tolerant of losing a copy. Missense variants: 173 observed, 179.59 expected, observed/expected ratio (o/e) 0.96, 90% interval 0.85 to 1.09. Synonymous variants: 52 observed, 65.6 expected, observed/expected ratio (o/e) 0.79, 90% interval 0.63 to 1.
Homologues: Orthologues: chimpanzee NABP1 (99% identical), pig NABP1 (92% identical), macaque NABP1 (88% identical), guinea pig NABP1 (85% identical), mouse Nabp1 (81% identical), dog NABP1 (75% identical), rat Nabp1 (72% identical), zebrafish nabp1a (64% identical), zebrafish nabp1b (54% identical), Drosophila melanogaster CG5181 (42% identical). Paralogues in human: NABP2 (56% identical).
Diseases named in the same sentence as NABP1 in open-access papers:
NABP1 is named in the same sentence as 15 diseases in open-access papers, as found by Europe PMC text mining. Sharing a sentence is not in itself a finding about the gene and the disease. The quoted sentences say what the papers report.
leukemia (1 paper, 2020). A malignant (clonal) hematologic disorder, involving hematopoietic stem cells and characterized by the presence of primitive or atypical myeloid or lymphoid cells in the bone marrow and the blood. "miR-494-3p was mainly paired with immune genes (CD3G, CXCL13, CXCR5, KLRC4), some of which had been annotated as oncogenes in leukemia including IGF1 (DRG; pan-cancer), IKZF3 (driver; leukemia), NABP1 (oncogene; leukemia), and PDGFRA (oncogene; pan-cancer)." (PMID 32605588, 2020).
tumor (5 papers, 2014 to 2025). "We demonstrated in a pool of primary CRC samples the significant decrease of NABP1 mRNA levels in tumor tissue compared to normal mucosa, strengthening observations on gene expression." (PMID 31429725, 2019).
NABP1 also shares sentences with these, for which no sentence is quoted: cancer (6 papers); acute promyelocytic leukemia (2); breast carcinoma (2); laryngeal squamous cell carcinoma (2); acute stress disorder (1); bladder cancer (1); infectious disease (1); medulloblastoma (1); mental retardation (1); metabolic disorder (1); neurological disorders (1); renal carcinoma (1); skin disorder (1).